TMEM78 (transmembrane protein 78)
Synonyms: FLJ40168
Gene: Long non-coding RNA gene on chromosome 1 (229,249,636 to 229,251,810, forward strand). Ensembl gene ENSG00000177800.
Subcellular location: Membrane
Diseases named in the same sentence as TMEM78 in open-access papers:
TMEM78 is named in the same sentence as 1 disease in open-access papers, as found by Europe PMC text mining. Sharing a sentence is not in itself a finding about the gene and the disease.
TMEM78 shares sentences with these, for which no sentence is quoted: osteosarcoma (1 paper).